TNF (tumor necrosis factor)
Diseases named in the same sentence as TNF in open-access papers (continued):
Sharing a sentence is not in itself a finding about the gene and the disease.
silicosis (continued). "Furthermore, certain biomarkers, such as tumor necrosis factor-alpha (TNF-α) and club cell protein 16 (CC16), may serve as valuable indicators for the early detection of silicosis, thereby facilitating clinical decision-making in early diagnosis." (PMID 40376052, 2025). "Overall, the studies showed that increased TNF-α levels in silica-exposed workers without clinical signs of the disease could be a potential biomarker for diagnosing early silicosis." (PMID 36672608, 2022). "Interestingly, the secretion of TNF- α, which is a key mediator of silicosis, is not a common feature of silica-activated macrophages." (PMID 36341426, 2022). "However, recessive model (AA vs. AG+GG) of both TNF −308 A/G and −238A/G was not significantly related to silicosis in all populations." (PMID 30643011, 2019). "The initial search of databases identified 410 potentially relevant articles, of which 401 articles (including 81 animal studies, 282 not silicosis or TNF-α gene-308G/A researches) were rejected because of their obvious irrelevance to the purpose of this study." (PMID 24124578, 2013). "Therefore, antagonism of TNF-α may not constitute an appropriate clinical target in silicosis." (PMID 34360876, 2021). "Our findings observed that sRAGE were negatively correlated with TNF-α, IL-6, IL-1β, and ox-LDL (indicators of inflammation), but not TGF-β1 (indicator of fibrosis), suggesting that sRAGE might be an anti-inflammatory and not an antifibrotic marker in silicosis." (PMID 32351319, 2020).
cystic fibrosis (56 papers, 2006 to 2025). Autosomal recessive disorder caused by pathogenic variants in the CFTR gene (cystic fibrosis transmembrane conductance regulator), which encodes a chloride and bicarbonate channel expressed in epithelial cells, and follow the diagnosis criteria. "In the IB3-1 cystic fibrosis cellular model, NF-κB-dependent genes, including the gene encoding for the proinflammatory protein IL-8, generally are activated following infection with P. aeruginosa or treatment with TNF-α or IL-1β." (PMID 29089668, 2017). "Further supporting the role of the immune response in cystic fibrosis bone disease is the observation that the patients with a higher production of TNFα due to polymorphisms in TNFA and/or TNFα and TNFβ (LT-a) genes showed a decreased bone density." (PMID 36979360, 2023). "Chronic infection of cystic fibrosis lungs perpetuates pro-inflammatory cytokine production, leading to elevated levels of TNFα, IL-6 and IL-1β and reduced levels of IL-10." (PMID 36979360, 2023). "Consistently, digitoxin has also been reported to be a potent and efficacious suppressor of TNFα-dependent proinflammatory cytokine expression in cystic fibrosis cells and patients as well." (PMID 34773067, 2021). "For instance, children with cystic fibrosis show increased TNF-α levels counterbalanced by simultaneous synthesis of IL-10." (PMID 31500172, 2019). "Studies demonstrated that the inhibition of TRPA1 results in a relevant reduction of the proinflammatory cytokines IL-1β and TNF-α in cystic fibrosis patients." (PMID 29682158, 2018). "The ability of LPS isolated from A. baumannii 1053 (a clinical isolate from a patient with cystic fibrosis), to induce cytokine production (e.g., IL-6 and TNF), is similar to that of LPS isolated from E. coli O130 in murine bone marrow-derived macrophages." (PMID 28757686, 2017). "We therefore employed IB3-1 cystic fibrosis cells, incubated for 5 h with two concentrations (1 μM and 10 μM) of selected compounds, and then treated with TNF-α (100 μg/ml)." (PMID 29089668, 2017). "NTM infections are opportunistic diseases primarily affecting individuals with compromised immune systems, such as patients with cystic fibrosis, chronic obstructive pulmonary disease, renal failure, transplant recipients with chronic corticosteroid use, TNF-α, and leukemia." (PMID 38380095, 2024). "The predominance of IL-1β mirrors what has been reported clinically using respiratory isolates of Pa isolated during the early stages of Pa infections from patients with cystic fibrosis, whereas the increase in IL-6 and TNF-α has parallels to what was seen in chronic Pa infections." (PMID 38792820, 2024). "This association implies that the phenotypes seen during cystic fibrosis may lead to IBD and thus provides clinical support for a model where increased goblet cells and mucin in patients undergoing anti-TNF therapy exacerbates inflammation and IBD." (PMID 37643009, 2023). "In pediatric cystic fibrosis patients, chemerin levels were comparable to healthy controls and did not correlate with nutritional status and levels of interleukin-1 beta (IL-1b), interleukin-6 (IL-6) and TNF α." (PMID 35327393, 2022). "Moreover, a clinical trial (phase II NTC 02649751) was investigating the function of roscovitine in the chronic inflammatory lung disease cystic fibrosis by monitoring pro- (TNF-α) and anti-inflammatory (IL-10) parameters, among others." (PMID 34502552, 2021). "Furthermore TRPA1 specific inhibitors from Hydra Biosciences (HC-030031) and Abbott (A-967079) inhibited P. aeruginosa induced transcription of IL8, IL1b, IL6 and tumor necrosis factor α (TNFα) in A549 and human cystic fibrosis cell line (CuFi-1)." (PMID 27827953, 2016).
cystic fibrosis (continued). "As persistent lower airway infection contributes to the lung pathology exhibited in cystic fibrosis, the peptides were also assessed for their ability to reduce the production of tumor necrosis factor-alpha (TNF-α) in response to pro-inflammatory bacterial lipopolysaccharides (LPS)." (PMID 26221537, 2014). "In addition, AZM significantly reduces the expression of the proinflammatory cytokine IL-1β and the chemokine C-C motif ligand (CCL)-2 and TNF-α in M1-induced cystic fibrosis alveolar macrophages in patients with cystic fibrosis." (PMID 24632748, 2014). "In addition, estrogen has been shown to aggravates inflammation in pseudomonas aeruginosa pneumonia in cystic fibrosis mice via increasing the total white blood cell counts and neutrophils, Th1 cytokines (TNF-α and IL-6) Th2 cytokines (IL-5) and extaxin." (PMID 22563373, 2012). "In cystic fibrosis mice, azithromycin attenuated cellular infiltration in both baseline and induced inflammatory condition, and inhibited cytokine (tumor necrosis factor-α and macrophage inflammatory protein-2) release in lipopolysaccharide-induced inflammation." (PMID 17064416, 2006). "A randomized controlled trial revealed that vitamin D deficiency is common in patients with cystic fibrosis, and high-dose vitamin D therapy can help regulate the inflammatory response of CF by reducing levels of the inflammatory cytokines TNF-a and IL-6." (PMID 37612740, 2023). "This bacteria is reported to enhance inflammation by increasing the production of cytokines such as IL-6, TNF-α, and G-CSF as seen in the case of cystic fibrosis." (PMID 35579429, 2022). "Studies on cystic fibrosis revealed that the levels of proinflammatory cytokines including IL-1, TNF, IL-6 and IL-8 are higher in CF patients while level of IL-10 is lower comparing to healthy individuals." (PMID 35139898, 2022). "On the other hand, a previous study reported that the tumor necrosis factor-α level was significantly higher in the cystic fibrosis group than in a control group, which might have resulted from bacterial infections, such as with Staphylococcus aureus, or from other microorganisms." (PMID 29267535, 2018). "TNFα and IL-17–asscoaited inflammatory responses increase CFTR modulator efficacy, suggesting reconsideration of pros and cons of suppressing inflammation in cystic fibrosis." (PMID 38888974, 2024). "Additionally, TNFα and IL-17-induced RANKL production in osteoblast from cystic fibrosis patients was reverted via treatment with a CFTR modulator." (PMID 36979360, 2023). "In addition, patients with cystic fibrosis are 7 times more likely to have IBD, a disease characterized by elevated levels of TNF." (PMID 37643009, 2023). "Additionally, TNFα and IL-17 further stimulate the production of RANKL via osteoblasts from cystic fibrosis patients." (PMID 36979360, 2023). "However, in our own studies of cystic fibrosis patients, we observed that chronic AZM treatment significantly lowered inflammatory gene expression including iNOS and TNF-α, but did not significantly increase M2-associated gene expression." (PMID 26597676, 2015). "In well differentiated human airway epithelial cells (HAE) from cystic fibrosis and non-CF patients, combined treatment with IL-1β and TNFα led to a decrease in transmembrane potential and tight junctional barrier function, the changes appearing more rapidly in CF cells." (PMID 21619599, 2011). "LDNs were generated from healthy NDNs in vitro by activation with TNF, LPS or fMLF, suggesting a mechanism of LDN generation in disease however, we show neutrophilia in people with Cystic Fibrosis was not due to increased LDNs." (PMID 34168640, 2021).
hidradenitis suppurativa (56 papers, 2018 to 2026). A chronic suppurative and cicatricial disease of the apocrine glands occurring chiefly in the axillae in women and in the groin and anal regions in men. "Recently, TNF-alpha inhibitors adalimumab, etanercept, and infliximab have been used to treat resistant AC, a variant of severe inflammatory acne and part of the follicular occlusion tetrad (i.e., AC, hidradenitis suppurativa, dissecting cellulitis and pilonidal disease)." (PMID 33655144, 2018). "Monoclonal antibodies targeting tumor necrosis factor-alpha (TNF-α) have transformed the management of moderate-to-severe hidradenitis suppurativa (HS)." (PMID 41809285, 2026). "Hidradenitis suppurativa (HS) is a chronic inflammatory skin disorder marked by dysregulated TNF-α signaling and aberrant adaptive immune responses, yet the role of humoral autoimmunity in disease pathogenesis remains incompletely understood." (PMID 42022889, 2026). "Single-cell transcriptomic network analysis identified dermal fibroblasts as the dominant cell communication hub in hidradenitis suppurativa and in mice injected with IL-17 and TNF." (PMID 41929214, 2026). "Hidradenitis suppurativa (HS) is an inflammatory, chronic skin disease characterized by recurrent abscesses, with a key role of tumor necrosis factor-alpha (TNF-α) in the pathogenesis." (PMID 41142785, 2025). "Shedding light on Hidradenitis Suppurativa activity: a pilot study to evaluate the potential of [99mTc]Tc-anti-TNF-alpha scintigraphy." (PMID 40872580, 2025). "Although inhibition of TNF-alpha is beneficial in hidradenitis suppurativa patients, the blockade of this inflammatory pathway can lead to the dysregulation of other cytokines and the subsequent paradoxical reaction seen in this patient." (PMID 40546629, 2025). "The most frequent reason for the e-consult was paradoxical psoriasiform lesions (n = 13, 33.3%), commonly related with anti-tumor necrosis factor agents (70% of the patients) and hidradenitis suppurativa (n = 4, 10.3%)." (PMID 38469167, 2024). "We investigated the effect on adipose tissue (AT) inflammation and mitochondrial respiration in patients with hidradenitis suppurativa (HS) after 12 weeks of treatment with adalimumab, a TNF‐α inhibitor." (PMID 39358901, 2024). "The keywords used during the search were: “anti-TNF drugs on HS”, “TNF-α inhibitors”, “anti-TNF treatment hidradenitis suppurativa”, “retinoid treatment hidradenitis suppurativa”, “hidradenitis suppurativa”, “TNF-α”, and “anti-TNF therapy”." (PMID 39712699, 2024). "Th17/ILC3 lymphocytes, with high levels of IL-1β, TNF-α, IL-17 and peripheral recruitment of IL-17-producing neutrophils and Th17-cells represent the main hallmarks of hidradenitis suppurativa immune response pattern." (PMID 37484864, 2023). "Tumor necrosis factor α inhibitors (TNFi) are a class of biologics approved to treat immune-mediated skin diseases, such as moderate-to-severe plaque psoriasis and hidradenitis suppurativa." (PMID 37304177, 2023). "Hidradenitis suppurativa is a chronic inflammatory disorder of the skin, which can be treated by tumor necrosis factor-α (TNFα) inhibitor therapy." (PMID 36381912, 2022). "The occurrence of hidradenitis suppurativa during SAPHO course supported the introduction of TNF-α blockers with a favourable result, as reported in a few cases in literature." (PMID 33187546, 2020). "After SAPHO diagnosis, NSAIDs therapy was started but the onset of bilateral gluteal hidradenitis suppurativa required the switch to a TNF-α antagonist (Adalimumab) with the achievement of a good control of the disease." (PMID 33187546, 2020). "Immunomodulation with anti‐TNF‐α is highly effective in the treatment of various immune‐mediated inflammatory diseases, including hidradenitis suppurativa (HS)." (PMID 31577850, 2020). "Notably, the patient also presented with hidradenitis suppurativa, a chronic inflammatory skin condition involving TNF-α and IL-1β pathways." (PMID 41409927, 2025).
hidradenitis suppurativa (continued). "Treatment of LPP using adalimumab resulted in a remarkable improvement in signs and symptoms as well as hair regrowth in two patients; One was refractory to a previous TNF inhibitor (certolizumab pegol) and was simultaneously affected by hidradenitis suppurativa (HS) and RA." (PMID 38335182, 2024). "The use of tumor necrosis factor-alpha (TNF-alpha) inhibitors, namely adalimumab, has significantly advanced the management of hidradenitis suppurativa, but the optimal biomarkers to monitor systemic inflammation and therapeutic response remain debated to this day." (PMID 41458786, 2025).
staphylococcus aureus infection (56 papers, 2013 to 2026). An infectious process in which the bacteria Staphylococcus aureus is present. "KEGG pathway analysis highlighted several pathways associated with innate immune responses, including cytokine secretion, complement and coagulation cascades, IL-17 signaling, TNF signaling, Staphylococcus aureus infection, and metabolic pathways." (PMID 40159598, 2025). "KEGG analysis highlighted pathways such as neutrophil extracellular trap formation, Staphylococcus aureus infection, complement and coagulation cascades, IL-17 signaling pathway, leukocyte transendothelial migration, and TNF signaling pathway." (PMID 41000384, 2025). "KEGG analysis showed enrichment of DEGs in diverse biological activities such as NOD-like receptor signaling pathway, TNF signaling pathway Staphylococcus aureus infection, and Neutrophil extracellular trap formation." (PMID 40433617, 2025). "Staphylococcus aureus infection induces severe inflammation, which leads to significant upregulation of TNF-α, IL-1β, and IL-6 in both lung tissues and cells." (PMID 38803378, 2024). "Staphylococcus aureus infection triggers early cytokine secretion, such as TNF-α, IL-1β, and IL-6, which promotes the inflammatory response and recruits other immune cells to combat invading microorganisms." (PMID 35935196, 2022). "Among these pathways, inflammation-related pathways were mostly enriched, such as Herpes simplex infection, Phagosome, Staphylococcus aureus infection, Focal adhesion, TNF signaling pathway, and IBD." (PMID 35509309, 2022). "KEGG pathway analysis of lesional versus non-lesional skin identified upregulated cytokine-receptor interaction (Q = 1.92E-7), TNF signaling (Q = 9.20E-8), and staphylococcus aureus infection (Q = 5.06E-7)." (PMID 35872776, 2022). "Upregulated KEGG pathways comprise staphylococcus aureus infection (Q = 4.42E-15), cytokine-receptor interaction (Q = 3.05E-12), and TNF signaling (Q = 4.02E-8)." (PMID 35872776, 2022). "An over-representation analysis, including all differentially expressed genes using the KEGG database, showed that the “TNF signaling” and “Staphylococcus aureus infection” pathways were enriched (FDR < 0.05)." (PMID 34422669, 2021). "TNF signaling and bacterial invasion of epithelial cells were only enriched for upregulated genes in head kidney, while evidence for Staphylococcus aureus infection and phagosome upregulation was liver-specific." (PMID 33676414, 2021). "We recently demonstrated that both CTLA4 Ig and anti-TNF treatment aggravate systemic Staphylococcus aureus (S. aureus) infection in mice, but with distinct clinical manifestations." (PMID 28264025, 2017). "Moreover, AP-1 directly regulates the transcription of inflammatory mediators (TNF-α, IL-2, IL-12, IL-1β, IL-8) and their receptors (IL-2R) in the cytokine–cytokine receptor interaction and Staphylococcus aureus infection pathways." (PMID 40647090, 2025). "In addition, the tumor necrosis factor (TNF) pathway and Staphylococcus aureus infection were found to have more significant roles too." (PMID 37904457, 2023). "Additionally, there were several inflammatory pathways upregulated in CCR2hi OCPs only in CIA: including Staphylococcus aureus infection, Toll-like receptor signaling and TNF signaling." (PMID 36591261, 2022). "KEGG analysis of stage I endometrial carcinomas vs. atrophic endometrium revealed staphylococcus aureus infection, estrogen signaling pathway, IL-17 signaling pathway, Renin secretion, inflammatory response, JAK/STAT3, K-Ras, and TNFα/NF-κB." (PMID 37958433, 2023). "The KEGG results indicated that upregulated genes were enriched predominantly in pathways related to influenza A cytokine-cytokine receptor interaction, cell adhesion molecules (CAMs), Staphylococcus aureus infection, NOD-like receptors, chemokines and TNF signaling pathways." (PMID 34737761, 2021).
staphylococcus aureus infection (continued). "The top enriched KEGG pathways included TNF signaling pathway, NF-κB signaling pathway, HIF-1 signaling pathway, cell adhesion molecules, and staphylococcus aureus infection, indicating that these pathways may play a crucial role in the pathogenesis of CRSwNP." (PMID 27216292, 2016). "Berberine’s mechanism of action may also be derived from inhibition of genes related to TNF-α, AGE-RAGE, and inflammatory signaling pathways in the context of Staphylococcus aureus infection, though further work using in vitro models is needed to further shed light on the potential mechanisms." (PMID 41517611, 2026).